FABP4 (fatty acid binding protein 4)
Diseases named in the same sentence as FABP4 in open-access papers (continued):
Sharing a sentence is not in itself a finding about the gene and the disease.
acromegaly (1 paper, 2021). Acromegaly is an acquired disorder related to excessive production of growth hormone (GH) and characterized by progressive somatic disfigurement (mainly involving the face and extremities) and systemic manifestations. "This is noteworthy to point that the correlation analysis of this study showed a linear association between FABP-4 level and HbA1c in the acromegaly group." (PMID 34217172, 2021). "Depending on the hypothesis that FABP-4 was closely relevant to glucose metabolism impairment, we aimed to evaluate FABP-4 levels in patients with acromegaly, especially patients with acromegaly-associated DM." (PMID 34217172, 2021). "In conclusion, the FABP-4 level was determined to be higher in the patients with acromegaly having DM and it may be a helpful predictor of acromegaly-associated DM." (PMID 34217172, 2021). "The FABP-4 may be a helpful predictor of acromegaly-associated DM." (PMID 34217172, 2021). "We aimed to investigate the possible effect of FABP-4 on glucose metabolism in patients with acromegaly." (PMID 34217172, 2021). "Logistic regression analysis suggested that the FABP-4 is an independent predictor of DM in acromegaly (β = 7.382, OR = 38.96, 95% CI: 1.52-5.76, p = 0.018)." (PMID 34217172, 2021). "According to the results of the present study, the FABP-4 level was found to be higher in patients with acromegaly and DM." (PMID 34217172, 2021). "Although adequate data in the linkage between FABP-4 level and type 2 DM have been presented in the literature, as far as we know, the association between FABP-4 and DM in acromegaly was not investigated before." (PMID 34217172, 2021). "We established that the FABP-4 is positively correlated to FPG, HbA1c, and GH levels in the acromegaly group (r = 0.548; p = 0.003, r = 0.478; p = 0.012, r = 0.418; p = 0.027, respectively)." (PMID 34217172, 2021). "Logistic regression analysis also suggested that the FABP-4 level is an independent predictor of DM in acromegaly but not age, sex, IGF-1, and GH." (PMID 34217172, 2021). "The results of the present study demonstrated that FABP-4 levels were higher in the patients with acromegaly having DM compared to the patients without DM and the controls." (PMID 34217172, 2021). "The difference in FABP-4 levels between all patients with acromegaly and the control group was not statistically significant (p = 0.286)." (PMID 34217172, 2021).
adrenocortical carcinoma (1 paper, 2022). "Human adipose stem/stromal cells induced to differentiate in co-cultures with the adrenocortical carcinoma cell line (H295R) showed lower levels of proteins normally associated with functional adipocytes, such as adiponectin, Fatty Acid-Binding Protein 4 (FABP4) and Hormone-Sensitive Lipase (HSL)." (PMID 35441960, 2022).
AIDS (1 paper, 2025). A syndrome resulting from the acquired deficiency of cellular immunity caused by the human immunodeficiency virus (HIV). "Strikingly, the expression of FABP4 is also detected in cerebrospinal fluid (CSF) of AIDS-associated cryptococcosis patients." (PMID 39714095, 2025).
Airway obstruction (1 paper, 2016). Obstruction of conducting airways of the lung. "In addition, we also found that FABP4 levels were associated with FEV1% predicted in COPD patients which suggests FABP4 may be correlated with airway obstruction." (PMID 26823558, 2016).
aneurysm (1 paper, 2020). Bulging or ballooning in an area of an artery secondary to arterial wall weakening. "Third, it would be interesting to compare non-ruptured aneurysm patients with matched healthy controls to address the problem of measuring FABP4 levels after aneurysm rupture on admission." (PMID 32075656, 2020).
autoimmune thyroiditis (1 paper, 2022). "Increased FABP4 concentrations were observed in both hypothyroid and hyperthyroid individuals as well as in autoimmune thyroiditis." (PMID 36561568, 2022).
bacterial pneumonia (1 paper, 2023). Acute infection of the lung parenchyma caused by bacteria (e.g., Streptococcus pneumoniae, Haemophilus influenzae, Chlamydia pneumoniae, Mycoplasma pneumoniae, and Legionella pneumophila). "It was also shown that FABP4 in lung macrophages is important for neutrophil recruitment and that FABP4 null mice were less resistant to bacterial pneumonia." (PMID 37207357, 2023).
Barth syndrome (1 paper, 2019). Barth syndrome (BTHS) is an inborn error of phospholipid metabolism characterized by dilated cardiomyopathy (DCM), skeletal myopathy, neutropenia, growth delay and organic aciduria. "Increased FABP4 expression in TAZ517delG-iPS-CM suggests that FABP4 plays a role in TAZ-induced cardiac dysfunction, although the exact mechanism of FABP4 in the pathophysiology of Barth syndrome is not established yet." (PMID 31861102, 2019).
bone tumor (1 paper, 2013). "FABP4 positivity in bone tumor lesions was much higher than in benign prostate and primary tumor samples, indicating there might be a potential functional reason for its abundance in the bone metastatic niche." (PMID 24240026, 2013). "Among array-identified genes, three (i.e., FABP4, IL-1β, and HMOX-1) were also significantly induced in experimental PC3 bone tumors from HFD mice as compared to LFD mice." (PMID 24240026, 2013). "In an effort to explore localization of FABP4 in the bone tumor microenvironment, we performed immunohistochemical analyses of PC3 bone tumors from LFD and HFD mice." (PMID 24240026, 2013).
brain cancer (1 paper, 2025). A primary or metastatic malignant neoplasm affecting the brain. "In addition, specific FABP subtypes exhibit tissue- and context-dependent functions, with FABP4, FABP5, FABP6, and FABP7 being the most extensively studied in breast, liver, colorectal, and brain cancers." (PMID 40717587, 2025).
brain injury (1 paper, 2025). Acute and chronic (see also brain INJURIES, CHRONIC) injuries to the brain, including the cerebral hemispheres, CEREBELLUM, and brain STEM. "Conversely, fatty acid-binding proteins (FABP1, FABP3, FABP4, FABP7) decreased over time in uninjured infants but increased in those with brain injury, suggesting a role in exacerbating damage." (PMID 40924950, 2025).
brain tumor (1 paper, 2024). "Our objective is to validate four plasma biomarkers – glial fibrillary acidic protein (GFAP), neurofilament light (NEFL), matrix metalloprotease 3 (MMP3) and fatty acid binding protein 4 (FABP4) – and compare them with established brain tumor molecular markers and survival." (PMID 38879494, 2024).
calcification (1 paper, 2021). Process by which organic tissue becomes hardened by the physiologic deposit of calcium salts. "Medial arterial calcification is more specific than intimal calcification in patients with CKD-MBD, in which process FABP4 might also be involved." (PMID 34789046, 2021).
cerebral cavernous malformation (1 paper, 2019). A disorder characterized by malformations in the structure of the capillaries in the brain. "FABP4, a protein involved in VEGF-mediated endothelial cell proliferation and implicated in the development of cerebral cavernous malformations, was found to be 2.5–3 fold higher in Fontan patients compared to ASD patients." (PMID 31797976, 2019).
choroidal neovascularization (1 paper, 2025). An eye disorder described by the growth of new blood vessels that originate from the choroid through a break in the Bruch membrane into the sub–retinal pigment epithelium (sub-RPE) or subretinal space. "In addition, to obtain additional insight into the biological roles of ioFABP4 and ioFABP5, a morphological study of laser-induced choroidal neovascularization (CNV) models was performed using FABP4-deficiency and FABP4/5-deficiency mice." (PMID 40076418, 2025).
chronic lung disease (1 paper, 2024). According to the definitions of the American and British Thoracic Societies, including pulmonary functional tests, X-rays, and CT scans for items such as fibrosis, bronchiectasis, bullae, emphysema, nodular or lymphomatous abnormalities. "In addition, results from recent investigations have revealed the key contribution of adipokines [such as leptin, adiponectin, visfatin, adipolin, and fatty acid binding protein 4 (FABP4)] released from adipose tissue in the pathogenesis of chronic lung diseases." (PMID 39845836, 2024).
chronic pancreatitis (1 paper, 2014). A chronic inflammatory process causing damage and fibrosis of the pancreatic parenchyma. "Paradoxically, lower circulating levels of FABP4 found in chronic pancreatitis patients, and lean compared with obese type 1 diabetic patients." (PMID 24593955, 2014).
Combined hyperlipidemia (1 paper, 2023). "Of note, FABP4 plasma levels have been previously correlated to TG levels in an obese subgroup of patients with familial combined hyperlipidemia and among subjects with T2D." (PMID 36769659, 2023).
Constipation (1 paper, 2020). Infrequent or difficult evacuation of feces. "Effects of dietary supplementations and the FABP4 inhibitor, BMS309403, on the GI motility were also assessed in the mouse model mimicking constipation." (PMID 31562532, 2020).
epilepsy (1 paper, 2022). A brain disorder characterized by episodes of abnormally increased neuronal discharge resulting in transient episodes of sensory or motor neurological dysfunction, or psychic dysfunction. "The expression of PXR and fatty acid binding protein 4 (FABP4) were increased by Valproate (valproic acid, VPA), a widely used drug in the therapy of epilepsy, in a dose-dependent manner." (PMID 36111293, 2022).
experimental autoimmune encephalomyelitis (1 paper, 2025). An autoimmune demyelinating disease of the central nervous system that is produced experimentally in animals by the injection of homogenized brain or spinal cord in Freund's adjuvant. "Moreover, DCs deficient in FABP4 were found to be poor producers of proinflammatory cytokines, and Ag presentation by FABP4−/− DCs did not promote proinflammatory T‐cell responses in experimental autoimmune encephalomyelitis (EAE)." (PMID 40716098, 2025).
fatty acid metabolism disorders (1 paper, 2022). "FABP4 may play a key role in BMSC senescence caused by fatty acid metabolism disorders." (PMID 35088483, 2022). "Therefore, we speculate that FABP4 may play a role in cell senescence caused by fatty acid metabolism disorders." (PMID 35088483, 2022).
folate deficiency (1 paper, 2022). A nutritional condition produced by a deficiency of FOLIC ACID in the diet. "The expression of fatty acid-binding protein-4 (Fabp4), an intracellular lipid transporter, was also enhanced by folate deficiency." (PMID 35548560, 2022).
follicular adenomas (1 paper, 2018). "The strongest candidate genes which may be able to discriminate follicular adenomas and carcinomas, CRABP1, FABP4 and HMGA2, were validated in independent samples by qRT-PCR and immunohistochemistry." (PMID 29535811, 2018).
gastrointestinal stromal tumor (1 paper, 2021). "However, the role of FABP4, a member of the FABPs, in GISTs (Gastrointestinal stromal tumors) remains unclear." (PMID 34558731, 2021).
generalized lipodystrophy (1 paper, 2024). Almost complete absence of subcutaneous and/or visceral adipose tissue. "Even more surprisingly, transgenic mice overexpressing the nuclear form of SREBP-1c (nSREBP) in adipocytes under the control of the FABP4/Ap2 enhancer/promoter showed a phenotype resembling human congenital generalized lipodystrophy." (PMID 38727299, 2024).
Hashimoto thyroiditis (1 paper, 2022). An autoimmune disorder caused by the production of autoantibodies against thyroid tissue. "In euthyroid subjects with Hashimoto thyroiditis, FABP4 concentrations were higher than in healthy controls and were directly associated with T4 and insulin concentration." (PMID 35448487, 2022).
hemangioma (1 paper, 2022). A benign vascular lesion characterized by the formation of capillary-sized or cavernous vascular channels. "Previous studies have shown that the mTOR pathway is activated at sites of inflammation in RA and that activation of the mTORC1 pathway regulates FABP4 expression in hemangiomas;22,23 however, it remains unclear whether activation of the mTORC1 pathway regulates FABP4 expression in RA." (PMID 35729106, 2022).
Hydrocephalus (1 paper, 2020). Hydrocephalus is an active distension of the ventricular system of the brain resulting from inadequate passage of CSF from its point of production within the cerebral ventricles to its point of absorption into the systemic circulation. "In the present study, FABP4 levels were also correlated with increased risk of hydrocephalus, TCD cerebral vasospasm, and DCI after SAH." (PMID 32075656, 2020). "FABP4 was linked to hydrocephalus, and the unadjusted and adjusted risks were increased by 7% (OR 1.07, 95% CI 1.04–1.10) and 5% (OR 1.05, 95% CI 1.00–1.10), respectively." (PMID 32075656, 2020). "In addition, FABP4 showed promise as a biomarker for secondary neurological insults, including hydrocephalus, TCD cerebral vasospasm, and DCI, after SAH." (PMID 32075656, 2020).
hyperphosphatemia (1 paper, 2021). Abnormally high level of phosphate in the blood. "In this regard, we found that serum FABP4 positively correlated with iPTH and ALP, thus we speculate that elevated FABP4 may exacerbate the imbalance between bone formation and resorption, accentuate hyperphosphatemia, and consequently promote VC." (PMID 34789046, 2021).
hyperplasia (1 paper, 2025). An abnormal increase in the number of cells in an organ or a tissue with consequent enlargement. "In contrast, no statistical differences in the incidence rate of prostatic burdens (e.g., hyperplasia, PIN, primary adenocarcinoma, and metastasis) were observed between FABP4−/− TRAMP mice consuming HF or CD." (PMID 41226657, 2025).
infertile (1 paper, 2023). "In tri-lineage differentiation, menstrual blood-derived cells from both volunteers and infertile patients expressed FABP-4 for adipogenesis, osteocalcin for osteogenesis, and aggrecan for chondrogenesis." (PMID 37840125, 2023).
intrahepatic cholestasis (1 paper, 2026). A cholestasis characterized by impairment of the bile flow caused by obstruction located in the liver. "FABP4 may represent a novel biomarker reflecting the metabolic-inflammatory interplay underlying the pathophysiology of intrahepatic cholestasis of pregnancy." (PMID 41750674, 2026).
lactic acidosis (1 paper, 2023). Metabolic acidosis characterized by the accumulation of lactate in the body. "Briefly, we observed a significant decrease in FABP4, adiponectin, and perilipin-1 protein expression both in acADSCs grown under lactic acidosis and in those treated with TGFβ1 compared to basal conditions." (PMID 36980280, 2023). "Briefly, we demonstrated that acADSCs grown under lactic acidosis conditions lose the adipocyte differentiation markers FABP4, C/EBPα, adiponectin, and perilipin-1 while acquiring the myofibroblast markers α-SMA, COL1A1, and COL1A2." (PMID 36980280, 2023).
Lipedema (1 paper, 2022). Disorder of adipose tissue characterized by symmetric and bilateral enlargement of the lower extremities due to abnormal deposition of subcutaneous fat often in obese women. "This is partly supported by data showing significant upregulation of various adipogenic genes, including PPARγ, CD36/fatty acid translocase, and the fatty acid binding protein-4 (FABP4) in in vitro differentiated lipedema adipocytes from non-obese donors compared to non-lipedema controls." (PMID 36675759, 2022).
lipoma (1 paper, 2019). A benign, usually painless, well-circumscribed lipomatous tumor composed of adipose tissue. "The quantification of the bound ORO staining unequivocally revealed that lipoma-derived ASCs have a significantly weaker capacity to differentiate into the adipogenic direction as confirmed by downregulated FABP4, PPARγ, and LEP expression compared to ASCs of RP and SC fat." (PMID 31640774, 2019).
malignant glioma (1 paper, 2023). A grade III or grade IV glioma arising from the central nervous system. "They found that WNT10B and fatty acid-binding protein 4 (FABP4) were upregulated by RT-qPCR in malignant gliomas versus normal tissue." (PMID 36814601, 2023).
Miscarriage (1 paper, 2023). A pregnancy that ends at a stage in which the fetus is incapable of surviving on its own, defined as the spontaneous loss of a fetus before the 22th week of pregnancy. "Notably, increased FABP4 serum levels are widely associated with the risk of various pregnancy conditions, including miscarriage, GDM, PE, and premature delivery." (PMID 37628833, 2023).
nephrocalcinosis (1 paper, 2022). Nephrocalcinosis is a disorder that occurs when too much calcium is deposited in the kidneys. "A recent study demonstrated that lipid metabolism in renal papillary tissue containing RP was impaired, which was associated with the downregulation of FABP4 based on immunohistochemistry of human renal tissue, microarray analysis of nephrocalcinosis model mice and FABP4 knockout mice." (PMID 36034902, 2022).
nephrotic syndrome (1 paper, 2020). A collection of symptoms that include severe edema, proteinuria, and hypoalbuminemia; it is indicative of renal dysfunction. "Since levels of P-FABP4 were comparable in MCNS and MN in patients with nephrotic syndrome, the difference in U-FABP4 between the two groups would be attributable to new expression of FABP4 in the kidney." (PMID 33143633, 2020).
pneumonia (1 paper, 2026). An acute, acute and chronic, or chronic inflammation focally or diffusely affecting the lung parenchyma, caused by an infection in one or both of the lungs (by bacteria, viruses, fungi, or mycoplasma.). "The single gene FABP4, encoding a macrophage-associated lipid chaperone and recently described pneumonia biomarker, performs similarly when combined with alpha diversity; FABP4 protein alone achieves an AUC = 0.88 (95% CI 0.82-0.93)." (PMID 41974724, 2026).
primary lymphedema (1 paper, 2025). A congenital condition that results in swelling in the arms or legs, and can occur during adolescence or adulthood. "FABP4 binds both SFAs and PUFAs and has been implicated in primary lymphedema, with mutations near its nuclear localization signal suggesting a functional role in disease pathogenesis." (PMID 40759794, 2025).
psoriatic arthritis (1 paper, 2022). Joint inflammation associated with psoriasis. "Moreover, in one of the most recent studies performed on patients with psoriatic arthritis, it was shown that FABP-4 was elevated in patients with cardiovascular diseases and correlated with higher disease activity, as well as that FABP-4 gene expression was upregulated." (PMID 36144237, 2022).
Respiratory tract infection (1 paper, 2025). An infection of the upper or lower respiratory tract. "Having established FABP4’s significance in SARS-CoV-2 adipocyte infection, we investigated its role in human bronchial epithelial (HBE) cells to understand whether it is engaged early on during respiratory tract infection." (PMID 39843629, 2025).
schizophrenia (1 paper, 2023). A major psychotic disorder characterized by abnormalities in the perception or expression of reality. "This study aimed to explore the association of circulating FABP3/FABP4 levels with HRV in patients with chronic schizophrenia." (PMID 37255976, 2023). "Increased FABP3 and FABP4 levels may be associated with CVD-related health problems in patients with chronic schizophrenia." (PMID 37255976, 2023).
skin infection (1 paper, 2018). An inflammatory process affecting the skin, caused by bacteria, viruses, parasites, or fungi. "In a VACV skin infection model, fatty acid binding protein 4 and 5 (FABP4/5) were shown to be among the highest expressed genes in TRM cells, enabling the metabolism of exogenous free fatty acids in the skin." (PMID 30555481, 2018).